CXCL10 (C-X-C motif chemokine ligand 10)
Diseases named in the same sentence as CXCL10 in open-access papers (continued):
Sharing a sentence is not in itself a finding about the gene and the disease.
tumor (continued). "In the role of anti-tumor immunity, mast cells secreted CCL3 and CXCL10 to recruit NK cells, CD4+ helper T cells, and CD8+ cytotoxic T cells." (PMID 35563678, 2022). "Among them, two vital chemokines (CXCL9 and CXCL10), which trigger the recruitment of CD8+ T cells into the tumor microenvironment (TME) in BLCA, were upregulated in the high-GNG4 group." (PMID 35456499, 2022). "Among the molecules activated by STING signaling, IFNs can stimulate the generation of anti-tumor T cells, T-cell infiltration and the direct killing of cancer cells, whereas CXCL10 and CCL5 are important for recruiting tumor-reactive effector T cells." (PMID 36498833, 2022). "CXCL10 also potentiates the accumulation of CXCR3+ effector T cells, particularly CD8+ T cells, into the tumor microenvironment and directly suppresses tumor growth in various cancers." (PMID 36275816, 2022). "Tumour-derived chemokines such as CXCL9, CXCL10, and CXCL11 are attracted by CXCR3 (expressed on activated CD8+ T cells), leading to their recruitment and development of anti-tumour immune response." (PMID 35406451, 2022). "The expression of CXCL9, CXCL10 and CXCL11 is positively correlated with the density of tumor infiltrating NK and T cells." (PMID 35033066, 2022). "The intratumoural injection of oncolytic adenovirus expressing CXCL10 enhanced ACT and eradicated well-established tumours in a mouse model of myeloma." (PMID 35205725, 2022). "further revealed that silencing STAT3 in T cells allows CXCR3 (the receptor for CXCL10) to be expressed in CD8+ T cells, leading to CD8+ T cells effectively accumulating at tumor sites." (PMID 35530361, 2022). "Studies have shown that tumor-resident cDC1s are the main source of CXCL9 and CXCL1029, and CXCL10 is a candidate for cancer immunotherapy." (PMID 35710862, 2022). "The chemokine CXCL9, along with its two family members CXCL10 and CXCL11, promotes tumour-suppressive lymphocytic infiltration in solid tumours via its receptor CXCR3." (PMID 35314795, 2022). "IHC staining of tumor tissues from mice treated with B3GALT4 knockdown 9464D cells confirmed the expression levels of CXCL9 and CXCL10, and the percentage of CD8A-positive cells was increased after MβCD treatment, while caveolin-1 was decreased." (PMID 36284313, 2022). "Enhancer of zeste homolog 2 (EZH2), a PRC2 component, mediates histone H3 lysine 27 trimethylation and represses tumor production of CXCL9 and CXCL10." (PMID 34385592, 2022). "Exosomal mRNA analysis showed that CXCL10, CXCL11 and SAMD9 were highly expressed in CRC patients with liver metastasis, which was validated by tumor RNA sequencing using GSEA." (PMID 36230645, 2022). "Radiation combined with vaccination upregulates the expression of the chemokines CXCL10 and CCL5 in the tumour, along with increased CD8+ T cell infiltration." (PMID 35365161, 2022). "CXCL10 is a ligand for CXCR3 that is expressed on tumour-infiltrating lymphocytes and mediates CD8 T cell infiltration within tumour." (PMID 35148789, 2022). "Four hub mRNAs in this network, including CXCL10, CXCL11, CCL7, and CCL8, were identified which have also been demonstrated to influence the tumor microenvironment and infection status." (PMID 36544484, 2022). "Based on the promising findings on the prognostic relevance of baseline CXCL13 serum levels, we subsequently evaluated the potential regulation of CXCL1, CXCL10 and CXCL13 after tumor resection." (PMID 36077611, 2022). "Upon its secretion (primarily) by monocytes, CXCL10 initiates Th1 immune responses and importantly contributes to increasing the number of CD8+ T cells in the inflamed tumor microenvironment." (PMID 36612121, 2022). "CXCL9 and CXCL10 are chemokine ligands of CXCR3, which differ from other chemokines due to their ability to restrain tumor growth and enhance antitumor immunity." (PMID 35320940, 2022).
tumor (continued). "came to the identical conclusion, demonstrating that genetic or pharmacological inhibition of EZH2 induces re-expression of chemokine CXCL10 in HCC and therefore promotes migration and infiltration of NK cells into the tumor." (PMID 36685594, 2022). "In EGFR-mutant tumor cells cocultured with activated PBMCs, EGFR-TKI treatment increased CXCL10 in the supernatant; this activated CXCR3 in the tumor cells to induce the phosphorylation of Src and the NF-κB subunit, p65, and the expression of HIF-1α." (PMID 36612121, 2022). "IFN-γ-inducible CXCL9, CXCL10 and CXCL11 are chemokines for cytotoxic T cells, which attract more cytotoxic T cells to infiltrate into tumor tissues and exert anti-tumor effects." (PMID 35300424, 2022). "IFN-γ-inducible CXCL9, CXCL10, and CXCL11 are chemokines attracting cytotoxic T cells to infiltrate into tumor tissues and exert anti-tumor effects." (PMID 35300424, 2022). "The biological activity of GEN1046 on T cells was reflected by increases in IFNγ, TNFα, IL2, and CXCL10 in peripheral blood in MC38-hPD-L1 and MC38-WT tumor–bearing mice." (PMID 35176764, 2022). "M1-Mφs function as inhibiting tumor progression by secreting pro-inflammatory cytokines (IFN-α/β/γ and IL-12) and chemokines (CXCL9 and CXCL10), which can attract CTL and NK cell to restrict tumor growth." (PMID 35155237, 2022). "Consistent with this, the expression of T cell chemokine genes such as CCL3, CCL4, CCL5, CXCL9, CXCL10 and CXCL1123 in MKN74 tumours tends to be higher than that in other tumours, especially after ERY974 administration." (PMID 36071036, 2022). "In gastric cancer, TG2 upregulation was shown to enhance inflammation and promote tumor growth by recruiting macrophages to the tumor milieu via Il-1β-mediated induction of CCL2 and CXCL10." (PMID 35681474, 2022). "Recently, it has been reported that CDK4/6i can also induce metabolic stress in tumor cells, leading to expression of chemokines such as CCL5 and CXCL10 that can further enhance anti-tumor immune responses." (PMID 35248122, 2022). "When the tumor volume reached an average of 100 mm3, the mice were given a vehicle either alone or combined with SD70 and/or an anti-CXCL10 neutralizing antibody." (PMID 35121645, 2022). "In summary, we observed that when IFN-γ was neutralised, the production of CXCL10 and CCL5 within SCC tumours was notably impaired, which correlated with a significant reduction in infiltrating CD8+ T cell numbers." (PMID 33925140, 2021). "The expression levels of CXCL10, IGF1, MMP3, MMP1, ICAM1, and IL-13 were significantly up-regulated in tumor tissues." (PMID 34544905, 2021). "We verified that CXCL10 in the TME negatively correlates with prognosis in PAAD and positively correlates with tumor cell differentiation." (PMID 33681290, 2021). "On the other hand, rich expression of IFN-γ, CXCL9, and CXCL10 and significantly high CTLA-4 or PD-1+ CD8/CD4 T cells were observed in the tumor microenvironment of CMS 1 patients." (PMID 33968712, 2021). "In a study on liver graft injury and tumor recurrence after liver transplantation, CXCL10/CXCR3 signaling upregulated at liver graft injury induced mobilization and recruitment of Tregs, which further promoted tumor recurrence after transplantation." (PMID 34504204, 2021). "M1 macrophages produce high levels of CXCL9, CXCL10, and CCL5 that can promote cytotoxic T cell functions with host defense and in tumor." (PMID 34771482, 2021). "CD4+ T cell IFN-γ-inducible chemokines CXCL9, CXCL10, and CXCL11 recruit effector T cells to the TME, direct tumor infiltration, and are key players in T cell homing." (PMID 34012451, 2021). "Previous work demonstrated that CXCL10, an established DPP4 substrate, mediates T-cell migration and recruitment to tumour tissue in vivo." (PMID 33513866, 2021). "While little is known about CXCL4 expression in GBM, CXCL9, CXCL10 and CXCL11 are expressed by tumor cells." (PMID 34203660, 2021).
tumor (continued). "A transcriptomic analysis of human tumor liver tissue showed an increased expression of several chemokines, such as CCL20, CXCL10, and CXCL11, compared with adjacent non-tumor liver tissue." (PMID 35008212, 2021). "It has been reported that CTCs with higher CXCR3 expression can be recruited to the tumor site by ligands, including CXCL9, CXCL10, and CXCL11, which are known as IFNγ-inducible chemokines." (PMID 34539647, 2021). "IL-23+ macrophages expanded anti-tumorigenic Th17 cells that had a distinct phenotype known as Th1-like Th17 cells and promoted tumor-specific immune responses by secreting IFN-γ, CXCL9 and CXCL10." (PMID 33418929, 2021). "A strong positive correlation was revealed between CXCL10 expression and CD8+ T cell abundance in tumours." (PMID 33925140, 2021). "We then applied a comparative analysis of ACE2 and CXCL10 expression in LUAD and LUSC based on their expression score by normal and tumor cells." (PMID 33585826, 2021). "Our current findings further suggest an additional benefit of cGAS-STING-IRF3 axis activation owing to increased expression of the CXCL10 and CCL5 chemokines, leading to T cell tumor infiltration." (PMID 34488791, 2021). "As expected, we also saw CXCL1, CXCL8, CXCL10, CXCL11, CXCL13, and CXCL14 in tumor tissues were upregulated in the results of TCGA data and the difference was statistically significant (p < 0.05)." (PMID 34794429, 2021). "The CRC patients were then categorized into two groups according to the expression level of CTTCs (CXCL9, CXCL10, CXCL11, and CCL5) in tumor." (PMID 34539647, 2021). "Accordingly, these effector cells are recruited into tumor tissues by the CXCR3 ligands, CXCL9, CXCL10, and CXCL11." (PMID 34885241, 2021). "CXCR3 exerts its biological effects through engagement by three IFN-γ inducible ligands (CXCL9, CXCL10 and CXCL11) that are mainly secreted by monocytes, endothelial cells, fibroblasts and tumor cells." (PMID 33924428, 2021). "DPP4 inhibition blocks the cleavage of CXCL10 by DPP4, thereby increasing the chemotaxis of immune cells towards tumour tissue via the cognate receptor of CXCL10, CXCR3." (PMID 34771657, 2021). "CXCL9 (p = 0.027), CXCL10 (p < 0.001), CXCL11 (p = 0.002) and CXCL13 (p < 0.001) were significantly up-regulated in tumor tissues compared with tumor-adjacent tissues, while the expression of CXCL12 (p = 0.149) was down-regulated." (PMID 34321012, 2021). "(ii) RT also regulates the tumor microenvironment, increases the levels of chemokines CXCL10 and CXCL16 in the tumor microenvironment, and promotes the migration of CD8+T cells to the tumor site." (PMID 33465302, 2021). "Overall, our study sheds new light on the complexity of the chemokine network and the potential role of CXCL10 regulation by ACKR2 in many physiological and pathological processes, including tumour immunology." (PMID 33801414, 2021). "Our results showed that the expression of CXCL9, CXCL10, and CXCL11 was significantly higher in tumor than in adjacent normal tissues in 136 CRC patients." (PMID 34539647, 2021). "Analogous to MDMs and tumor tissue slices, DCs treated with PVSRIPO or Poly(I:C)-tfx generated more type-I/III IFNs and CXCL10 relative to other stimuli; LPS only affected DC phenotype at a high dose." (PMID 33767151, 2021). "IFN-γ is important for T cell, natural killer (NK) cell, and NKT cell trafficking into tumours through the induction of chemokines such as CXCL9, CXCL10, and CXCL11." (PMID 33809369, 2021). "Then, for CXCL10, we performed gene set enrichment analysis, survival analysis and clinical analysis, and we used CIBERSORT algorithms to estimate the proportion of tumor-infiltrating immune cells in COAD samples." (PMID 34559115, 2021). "M1-like macrophages achieve this suppressing effect by recruiting CD8+ T and NK cells to the TME through antigen presentation to the T-cell receptor (TCR) and the tumor-derived chemokine secretion of CXCL9, CXCL10, and CXCL11 to recruit and activate NK cells." (PMID 34209703, 2021).
tumor (continued). "CXCL9, CXCL10 and CXCL11 are chemoattractant cytokines for anti-tumor leukocytes that express CXCR3, such as effector T cells." (PMID 33446805, 2021). "The increased expression of six CXC chemokines (CXCL4, CXCL9, CXCL10, CXCL11, CXCL12, and CXCL13) was related to tumor progression." (PMID 33767987, 2021). "Together with CCL5, CXCL10 is a key player in driving NK cells and CD8+ T cells into the tumour bed." (PMID 33801414, 2021). "Mast cells release chemokines such as CXCL10, CLL3, and CCL5 that recruit CD8 T cells and CD4 T cells to the tumor." (PMID 34063789, 2021). "The reduced expression of FENDRR significantly decreased TNFα, and CXCL10 mRNA and protein expression, suggesting a potential role of FENDRR in tumor cell immunity." (PMID 34200642, 2021). "In tumor-bearing mice, cDC1 in TME secrete chemokines, such as C-X-C motif chemokine ligand 9 (CXCL9) and CXCL10 to recruit effector T cells to TME." (PMID 34359674, 2021). "IFN-induced STAT1 can subsequently activate chemokines, such as CXCL9, CXCL10, and CXCL11, which can recruit more CD8+ T cells to provide anti-tumor immunity." (PMID 34282238, 2021). "Constitutively active STAT3 signaling in tumor cells has been shown to downregulate chemokine expression, including CCL5 and CXCL10, which are functionally responsible for T cell recruitment." (PMID 33777927, 2021). "Cytokine profiling on tumor protein extracts showed a substantial increase in the expression of IL-1α and β, CXCL9 and CXCL10 in pre-terminal gal-9-KO tumors by comparison with WT and aggressive gal-9-KO tumors." (PMID 33664349, 2021). "IFN-γ also enhances blood vessel maturation to promote tumor vascular remodeling and inhibit tumor growth by reducing VEGF-A levels and increasing CXCL9, CXCL10 and CXCL11 levels." (PMID 34294146, 2021). "CD26/DPPIV cleaves CXCL10 to regulate its biological activity, and DPPIV inhibition prevents degradation of CXCL10, thus increasing CXCR3+ T lymphocyte levels and reducing tumor growth." (PMID 33777580, 2021). "Strong positive-correlations (r > 0.5, p < 0.05) were observed between the expression of CXCL10 and CCL5 and CD8+ T cell abundance in tumours, while CCL17 and CCL22 were negatively correlated (r < −0.5, p < 0.05) with CD8+ T cell infiltration." (PMID 33925140, 2021). "Many pre-clinical models have shown that eosinophils play a vital role in the tumor microenvironment (TME) and response to immunotherapy through increased expression of CCL5, CXCL9, and CXCL10." (PMID 34732251, 2021). "After data processing, we also found that the expression of CXCL1, CXCL10, CXCL11, CXCL13, and CXCL14 was significantly increased in tumor tissues, and the difference between CXCL10 was the most significant." (PMID 34794429, 2021). "The refined six gene tumor immune signature (IDO1, CXCL10, CXCL9, HLA-DRA, STAT1, IFNG) was carried on a sample of cases representative of the Sema4D HIS subtypes using basic nSolver analysis." (PMID 33776991, 2021). "Strikingly, a large proportion of the IFNγ signature genes were upregulated by SHP2 inhibition specifically in tumor cells in co-culture, including cytokines (CXCL9, CXCL10, CXCL11 and CCL5) and antigen presenting machinery (HLA-A, HLA-B and B2M)." (PMID 33446805, 2021). "IFN-γ-neutralisation abrogated SCC regression, significantly reduced CD8+ T cell-infiltration into SCC, and significantly impaired the secretion of CXCL9, CXCL10 and CCL5 within the tumour microenvironment." (PMID 33925140, 2021). "DCs, especially Batf3+ CD103+ cDC1, are essential in presenting tumor antigen and secreting cytokines, such as CXCL9, CXCL10, that regulate T cell function." (PMID 33718229, 2021). "To overcome this problem, we proposed to exploit this behavior by using three chemoattractants: CXCL10, CCL2 and CCL11, released by a biodegradable hydrogel (GlioGel) to produce a migration of tumor cells toward a therapeutic trap." (PMID 34830041, 2021).
tumor (continued). "Induced expression of CXCL10 by using poly-ICLC can also interact with CXCR3 on effector T cells, prompting their infiltration into tumor." (PMID 34771532, 2021). "Our data indicate, however, that antibody-treated mice did show reduced CXCL9, CXCL10, and CCL5 chemokine production within the tumour mass, and a corresponding reduction in the number of tumour-infiltrating T cells." (PMID 33925140, 2021). "JMJD3 also regulates tumor immunity in CRC by enabling the transcription of the Th-1 type chemokine (CXCL9 and CXCL10), and treating the primary cells of CRC with GSK-J4 leads to a reduction in the chemokine level." (PMID 33478063, 2021). "CIK cells recognize tumors mainly by chemokine ligand (CXCL) 9, CXCL10, and CXCL11, or by binding of CIK cell surface NKG2D receptor to tumor cell surface MHC class I chain-related protein A or B ligand 20,21." (PMID 33854636, 2021). "CAFs-3 from the primary tumor showed distinct expression of other chemokines and growth factors, such as C3, CCL5, IGF1, CXCL10, CXCL9, and CXCL14, in addition to CCL19 and IGF2." (PMID 34790166, 2021). "IFN-γ induces both CXCL10 and CCL5, and both chemokines showed a strong positive correlation with CD8 T cell infiltration into tumours." (PMID 33925140, 2021). "Using the median value (50–50 division), the expression level of CXCL9, CXCL10, CXCL11, and CCL5 in tumor or adjacent normal tissues allowed the stratification of patients into groups." (PMID 34539647, 2021). "MMP-9 has been reported to cleave and potentially degrade T-helper cell 1 (Th1)-type chemokines like CXC ligand CXCL10 and inhibit their anti-tumor outcome, including the recruitment of CD4+ T cells and CD8+ T cells, and their tumor-killing effect." (PMID 34959271, 2021). "CTTCs including CXCL9, CXCL10, CXCL11, and CCL5, which were differentially expressed between tumor and adjacent normal tissues, were significantly correlated with the abundance of several OTUs." (PMID 34539647, 2021). "Furthermore, our group previously provided the first evidence for N-terminally cleaved antagonistic CXCL10 in malignant high-grade serous ovarian tumour samples but not benign ovarian disease and suggested that this was responsible for reduced lymphocyte infiltration in these tumours." (PMID 33513866, 2021). "The primary tumor responded to PD1, OX40, and PD1+CTLA4 treatment with increased production of IFNg, and accompanying increases in the IFN-regulated chemokine IP-10 (CXCL10) and the proinflammatory chemokine RANTES (not shown)." (PMID 34221953, 2021). "We found that whole-tumor gene expression of T cell marker factors (CD8 and IFN-γ) and chemokines (CXCL9 and CXCL10) were significantly enhanced after ICT treatment, while inflammatory factors (IL6, IL10 and TNF-α) were reduced." (PMID 33460401, 2021). "The expression of CXCL9, CXCL10, and CXCL11 except for CCL5 was significantly higher in the tumor compared with the adjacent normal tissues (p = 0.0707, p = 0.0001, p < 0.0001, and p = 0.4207)." (PMID 34539647, 2021). "To explore the difference in the CXCL10/CXCR3 biological axis between normal and tumor tissues, we performed GEPIA database analysis, which showed that the CXCL10 gene was significantly overexpressed in CC." (PMID 34345201, 2021). "In vivo, we demonstrate the importance of CXCL10/CXCR3 signaling in the maintenance of an inflammatory microenvironment, and that its blockage drives tumor progression." (PMID 34328416, 2021). "M1 macrophages suppressed angiogenesis and growth of CRC and pancreatic ductal adenocarcinoma (PDAC) cells through the enhanced production of CXCL9, CXCL10 and CXCL11 in “tumor-on-chip” system in vitro." (PMID 34209679, 2021). "During inflammation, tumor infiltrating immune cells produce INF-γ, which in turn activates a variety of INF-γ-induced genes through the JAK/STAT pathway, such as CXCL9, CXCL10 and CXCL11." (PMID 34200459, 2021).